STAT3 (signal transducer and activator of transcription 3)
Diseases named in the same sentence as STAT3 in open-access papers (continued):
Sharing a sentence is not in itself a finding about the gene and the disease.
ovarian carcinoma (continued). "Here, by utilizing high-throughput RNA-Seq-based screening and the related reports on CD97 promotes EMT and metastasis of ovarian cancer cells by activating the JAK2/STAT3 pathway 14, we found that the prometastatic factor CD97 could be a critical mediator of IL-8-induced promotion of EMT." (PMID 37907543, 2023). "Thus, it would be of great interest to further investigate whether upregulation of FAM46A in ovarian cancer chemo-resistance is attributed to NF-κB and/or STAT3-mediated transcriptional upregulation." (PMID 35465837, 2022). "We found that CAFs from malignant fluids of ovarian cancer receive a specific signaling pattern from cancer cells, mainly composed of ligands associated with neovascularization processes, differentiation pathway, EGFR tyrosine kinase inhibitor resistance, and IL-6/JAK/STAT3 signaling." (PMID 36352420, 2022). "Moreover, it has been proven that MEL activates the death receptors and inhibits the JAK2L/STAT3 pathway, leading to the inhibition of ovarian cancer cell growth; it can also decrease the expression levels of p-AKT and ERK1/2, and suppress the Rac1-dependent pathway." (PMID 35268753, 2022). "In summary, our results support the novel small molecule LLL12B as a potent STAT3 inhibitor in human ovarian cancer cells and suggest that LLL12B in combination with the current front-line chemotherapeutic drugs cisplatin and paclitaxel may represent a promising approach for ovarian cancer therapy." (PMID 33909625, 2021). "However, it is unknown whether PARPi treatments increase STAT3 activation in ovarian cancer patient tumors." (PMID 34956861, 2021). "Thus, blocking the activation of JAK2 and STAT3 via inhibitors, siRNAs, or neutralizing IL-6 could suppress ovarian cancer cell migratory capacity, making them possible targets for future therapeutic approaches." (PMID 34440886, 2021). "To further investigate whether STAT3 targeting could reverse Olaparib resistance in ovarian cancer cells, we incubated Olaparib-resistant ovarian cancer cells for 48 h with the STAT3 inhibitor Napabucasin, which was shown to impair tumor progression and cisplatin resistance." (PMID 34956861, 2021). "Furthermore, a recent publication demonstrates that Olaparib-treated macrophages functionally suppress T cell-driven antitumor immune responses, and STAT3 activation has been reported to be essential for immune-suppressive macrophage differentiation in advanced epithelial ovarian cancer." (PMID 34956861, 2021). "Our results suggest that LLL12B is a potent STAT3 inhibitor in ovarian cancer, and that LLL12B in combination with the current front-line chemotherapeutic drugs cisplatin and paclitaxel may represent a promising approach for ovarian cancer therapy that warrants further study." (PMID 33909625, 2021). "Thus, a method for blocking the EGFR and STAT3 pathways in ovarian cancer needs to be developed." (PMID 34369236, 2021). "Notably, in ovarian cancer, in vitro studies have illustrated how IL-6 could induce, through STAT-3, the upregulation of HIF as well as overexpression of hexokinase and associated glycolytic pathway." (PMID 33550983, 2021). "Furthermore, existing evidence highlights the involvement of miRNA-containing EVs in the angiogenesis of ovarian cancer by indicating the contribution of miR-141-3p-carrying EVs in the angiogenesis of endothelial cells in ovarian cancer via the activation of the JAK/STAT3 and NF-κB pathway." (PMID 33407591, 2021). "Therefore, we tested the effects of the novel STAT3 inhibitor LLL12B on ovarian cancer cell migration and whether the effect of cisplatin and paclitaxel can be enhanced by LLL12B." (PMID 33909625, 2021). "Because PARPi combination with VEGF-inhibiting antibody bevacizumab has been shown to significantly improve progression-free survival in an ongoing recurrent ovarian cancer clinical trial, STAT3 inhibition may also improve PARPi effects through VEGF downregulation." (PMID 34956861, 2021).
ovarian carcinoma (continued). "In our study, the JAK/STAT3 signaling pathway was inhibited by NR1D1 over-expression and enhanced by NR1D1 silencing, indicating that the JAK/STAT3 signal may be implicated in the role of NR1D1 in ovarian cancer cells." (PMID 34330232, 2021). "Thus, we surmise that ovarian cancer cells might use STAT3 pathway activation to overcome EGFR inhibition, which leads to anti-EGFR antibody treatment failure." (PMID 34369236, 2021). "Altogether, above these results proved that p-STAT3/NF-kB was a crucial axis in the development of ovarian cancer for increasing the expression of IL-6 and VEGF which created a feedback loop to activate p-STAT3/NF-kB axis as a cascade amplification method, and At-EE could restrain this phenomenon." (PMID 32190078, 2020). "In our study, adding medium from cultured tumor cells or IL-6 and VEGF could abrogate the effect of At-EE inhibition of p-STAT3 activation and NF-kB phosphorylation, which demonstrated IL-6, VEGF, and p-STAT3/NF-kB created an autocrine feedback loop in ovarian cancer cells." (PMID 32190078, 2020). "Therefore, we hypothesized that STAT3 phosphorylation might be related to the biological behavior of PADI2-mediated ovarian cancer cells." (PMID 32951601, 2020). "Collectively, these data may inspire a new wave of clinical investigation that will provide important insights into the clinical benefits of eliminating immunosuppression and preventing therapy resistance of ovarian cancer by targeting the CD44/STAT3 axis in different TME resident cell types." (PMID 33335857, 2020). "Hence, STAT3 provides us an attractive target for ovarian cancer treatment and prevention." (PMID 31949487, 2020). "Abnormal activated STAT3 plays a crucial role in tumor properties such as migration, invasiveness, proliferation, survival, angiogenesis, cancer stem cell-like characteristic, and chemoresistance in ovarian cancer, driving it to act as a promising therapeutic target to manage this kind disease." (PMID 31949487, 2020). "Reduced expression of STAT3 in OC cells in vitro and in vivo via anti-miR551b-3p leads to reduction in growth of ovarian tumor in vivo, thereby implying that it could serve as promising therapeutic target in future for ovarian cancer." (PMID 31608277, 2019). "Platinum compounds may also trigger the ability of tumor cells to shape the immunosuppressive microenvironment, such as inducing M2 polarization of macrophages through the IL-6/STAT3 and NF-κB pathways; these changes indirectly contribute to the chemoresistance of cervical and ovarian cancers." (PMID 30927928, 2019). "Also, polyamine/NO adducts were found effective in the induction of ovarian cancer cell death via inhibition of signal transducer and activator of transcription 3 (STAT3), serine-threonine protein kinase AKT protein phosphorylation, and downregulation of their cytocolic levels." (PMID 31354753, 2019). "Importantly, STAT3 is required for ovarian cancer cells to grow in 3D." (PMID 31534498, 2019). "Thus, the activation of STAT3 at Y705 may mainly function to eliminate the cisplatin-induced autophagy in ovarian cancer cells." (PMID 31597912, 2019). "Likewise NO has been shown to suppress IL-6-induced STAT3 activation in ovarian cancer cells." (PMID 29800237, 2018). "Activation of STAT3 via phosphorylation at Tyr705 and the loss of the STAT3 inhibitor PIAS3 may serve as a tumor-initiating event in the distal fallopian tube for the formation of HGS ovarian cancer." (PMID 30042330, 2018). "In other words, p-STAT3 could play multiple roles in regulation of MMPs in ovarian cancer cells." (PMID 28859117, 2017). "Thus, a combination of irinotecan and STAT3 inhibitors might be plausible in treating ovarian cancers of immunoreactive subtype." (PMID 28691013, 2017). "Moreover, our future directions could include testing effects of STAT3 inhibitors on proliferation and progression of ovarian cancer in vivo." (PMID 28859117, 2017).
ovarian carcinoma (continued). "Therefore, Par3 may exert its oncogenic potential through the STAT3 pathway in a subset of ovarian cancer cells that are similar to JHOC5 cells." (PMID 27855669, 2016). "In addition, blockage of the JAK/STAT3 pathway inhibited ovarian cancer cell growth." (PMID 28536612, 2016). "Though the exact mechanism through which Par3 affects tumor formation remains to be investigated, our observations may explain how Par3 may be involved in tumor malignancy, which could be largely dependent on the reconstitution of STAT3 signaling in ovarian cancer." (PMID 27855669, 2016). "Indeed, raised levels of IL-6 in ascites and serum from ovarian cancer patients correlate with cisplatin and paclitaxel resistance and poor disease prognosis, whereas blockade of STAT3 expression in ovarian cancer cells increases their sensitivity to paclitaxel." (PMID 22481932, 2012). "However, it still remains to be determined if activation by EGF or somatic-activating mutations in the kinase domain of EGFR has any effect on the production of IL-6 or GP130 family of cytokines that can lead to the activated status of STAT3 in ovarian carcinomas." (PMID 19088723, 2009). "Hence, diminution in EGFR/IL-6R/STAT3 signalling may represent novel therapeutic targets for pharmacological intervention in the management of ovarian cancer progression." (PMID 19088723, 2009). "In addition, we report that the JAK2/STAT3 pathway is required to sustain EGF-induced EMT-associated phenotypes in ovarian cancer cells, indicating that in EGF-driven ovarian tumours JAK2/STAT3 signalling may be critical in regulating metastasis." (PMID 19088723, 2009). "Triptolide has been demonstrated in ovarian cancer cell lines and animal models to reduce ovarian cancer chemoresistance by interrupting PI3K/AKT/GSK3‐β and JAK/STAT3 signaling pathways." (PMID 40968783, 2026). "Through the IL‐6/STAT3/HIF‐1α feedback loop, IL‐6 aggravates cisplatin resistance in ovarian cancer cells." (PMID 40968783, 2026). "Related pathways such as Wnt/β‐catenin, STAT3, and PI3K/Akt are also involved in modulating ovarian cancer drug sensitivity status." (PMID 40968783, 2026). "Kaempferol has also showed antiproliferative effects in various human ovarian cancer cells (Caov‐3, TOV‐112D, SKOV‐3, and OVCAR‐3) by inducing autophagy and apoptosis G0/G1 cell cycle arrest and inhibition of MEK/ERK and STAT3 pathways." (PMID 40634118, 2025). "Increased levels of HMGA2 then binds to the promoter of STAT3 for increased transcription, leading to NOF activation to promote growth and metastasis of ovarian cancer cells." (PMID 40265981, 2025). "In addition, along with other studies, we also found that PTPN4 functions as a tumor suppressor in OC mainly by inhibiting the phosphorylation of STAT3, which may further hinder the activation of the subsequent pathway and inhibit ovarian cancer tumor growth and metastasis." (PMID 40145330, 2025). "In epithelial ovarian cancer, ALDH1A2 suppresses signal transducer and activator of transcription 3 (STAT3) signaling, a pathway known to promote tumor proliferation and migration." (PMID 39781359, 2025). "Another study reported that CAFs secrete sEVs carrying miR-296-3p, which exacerbates ovarian cancer progression by targeting PTEN and SOCS6, and stimulating the Akt/STAT3 pathway." (PMID 40008006, 2025). "Such an understanding of the crosstalk between CCL23, STAT3, and CXCL10 provides new insights into future therapeutic targets and improving the responsiveness of ovarian cancers to current immune-oncology therapies." (PMID 41463176, 2025). "The second in vitro study suggests that FV‐429, which is a wogonin derivative, can block the c‐Src, STAT‐3, and HIF‐1 mechanisms of action to mitigate paclitaxel resistance in ovarian cancer cells." (PMID 41164269, 2025).
ovarian carcinoma (continued). "In ovarian cancer (OC) cells, MYB overexpression induces cisplatin resistance by activating the NF-κB and STAT3 signaling pathways, whereas MYB silencing or inhibition restores cisplatin sensitivity." (PMID 40725394, 2025). "In ovarian cancer, cardamonin suppresses M2 polarization and reduces TAM-mediated tumor support by inhibiting the mTOR signaling pathway and STAT3 activation." (PMID 40330466, 2025). "Among various cancers, copy-number deletion of PIK3R1 is most commonly observed in ovarian cancer, where its deletion activates AKT and induces p110-independent JAK2/STAT3 signaling through phosphorylation changes in the docking protein Gab2." (PMID 40657399, 2025). "For example, in ovarian cancer, CHRF enhances cisplatin resistance through the regulation of the miR-10b and STAT3 pathways." (PMID 40612103, 2025). "The CHRF-miR-10b axis exerts a significant influence on cisplatin resistance in ovarian cancer (OC) through the regulation of the epithelial-mesenchymal transition (EMT) process and the STAT3 signaling pathway." (PMID 40612103, 2025). "In ovarian cancer, OSMR promotes tumor cell proliferation and metastasis by activating the STAT3 signaling pathway, and monoclonal antibodies targeting OSMR effectively suppressed cancer cell growth." (PMID 41498024, 2025). "For example, epithelial ovarian cancer cells release sEVs containing miR-141-3p, which, when absorbed by vascular endothelial cells, activate the JAK/STAT3 and NFκB signalling pathways, thereby enhancing angiogenesis." (PMID 40008006, 2025). "Continuous secretion of INAVA‐enriched EVs derived from ovarian cancer cells transfers INAVA mRNA to NOFs within the TME, thereby activating the INAVA/HMGA2/STAT3 axis and promoting NOF activation." (PMID 40265981, 2025). "Inhibition of CRM1-mediated nuclear export has been demonstrated to enhance the accumulation of mTOR in the nucleus, resulting in decreased protein levels of mTOR and its downstream targets, STAT3 and MMP9, in ovarian cancer cells." (PMID 41578763, 2025). "In ovarian cancer, BP1003 has demonstrated significant anti-tumor effects by reducing STAT3 levels, which in turn decreases cell viability, migration, and spheroid formation, especially when combined with chemotherapy agents like paclitaxel and 5-fluorouracil." (PMID 40330466, 2025). "This work demonstrates, for the first time, the generation and application of double-stranded DNA minicircles bearing three GAS-like motifs as inhibitors of STAT3 in vitro, using the highly chemoresistant SKOV3 cell line model for ovarian cancer." (PMID 41031165, 2025). "In ovarian cancer tissues and cell lines, miR-217 is downregulated, which leads to increased IL-6 secretion and the activation of the JAK2/STAT3 signaling pathway, driving M2-like macrophage polarization." (PMID 40330466, 2025). "Consequently, STAT3 activation fosters an aggressive ovarian cancer phenotype, contributing to treatment failure, poor prognosis and low survival rates, highlighting the urgent need for novel, safe, effective and affordable STAT3-targeted therapeutic strategies." (PMID 41031165, 2025). "In studies involving ovarian cancer cell lines (SKOV3, ES2, RMG1) and a murine ovarian cancer model, ONA inhibited cancer cell proliferation by suppressing STAT3 activation, a pathway crucial to cancer progression and chemoresistance." (PMID 40330466, 2025). "This study aimed to investigate the impact of chronic stress on HDC expression in ovarian cancer progression and the effect of HIS on the IL-6/STAT3/S100A9 pathway." (PMID 39720595, 2024). "Signal transducer and activator of transcription 3 (STAT3) is another important transcription factor that regulates proliferation, survival, metastasis and invasion of ovarian cancer." (PMID 40836974, 2024).
ovarian carcinoma (continued). "Recent study has revealed that STAT3 or TMEM205 co-localizes with EV secretion proteins, specifically Rab8 or Rab11, and its expression is upregulated in ovarian cancer cells, where it plays a crucial role in regulating EV secretion." (PMID 39414985, 2024). "Recent studies have shown that the IL-6/STAT3 signalling promotes CSC self-renewal and maintenance in ovarian cancer cells and supports tumor growth in the omental microenvironment." (PMID 38575576, 2024). "RNA-binding protein AUF1 promotes the biogenesis of hsa_circ_0010467 in ovarian cancer, which activates the LIF/STAT3 signaling pathway by mediating the inhibitory effect of miR-637 on leukemia inhibitory factor (LIF), thereby promoting platinum resistance." (PMID 39334866, 2024). "In research on epithelial ovarian cancer, EVs promote endothelial cell angiogenesis by activating the JAK/STAT3 signaling pathways." (PMID 39596828, 2024). "OCIAD2, part of the ovarian cancer immune response antigen (OCIA) domain family, promotes tumor metastasis by enhancing STAT3 activation and cell migration." (PMID 39445005, 2024). "We determined that TAMs had increased expression of IL-10, IL-6, CD206, and ARG1, whereas ovarian cancer cells had increased expression of IL-10, IL-6, VEGF, STAT3, and PD-L1." (PMID 36757936, 2023). "After inhibiting JAK2/STAT3 pathway, the promoting effect of CHAF1A on epithelial ovarian cancer cell proliferation disappeared, meanwhile the inhibitory effect of CHAF1A on apoptosis enhanced." (PMID 37575547, 2023). "CHAF1A promotes the proliferation and growth of epithelial ovarian cancer cells and inhibits the apoptosis of cancer cells by activating JAK2/STAT3 signaling pathway, which is expected to be a new target for the treatment of epithelial ovarian cancer." (PMID 37575547, 2023). "The same study revealed that SC144 inhibited STAT3 phosphorylation and subsequent expression of survivin, Cyclin-D2 and MMP-7 in a human ovarian cancer cell line." (PMID 36672405, 2023). "Glypican-3, ALDH1A1, TNFR2, STAT3, FOXP3, and TIM3 are increasingly recognised biomarkers to predict chemoresistance in women with ovarian cancer." (PMID 36768291, 2023). "Of interest, NANOG expression correlated positively with levels of total and phosphorylated STAT3, suggesting a role for NANOG-mediated EMT and drug-resistance through the activation of the STAT3 pathway in epithelial ovarian cancer." (PMID 37189618, 2023). "Moreover, the crosstalk between Jagged1/Notch and JAK/STAT3 signalling pathways may promote the aberrant occurrence of epithelial-to-mesenchymal transition, further reinforcing the invasion and migration abilities of platinum-resistant ovarian cancer." (PMID 37686015, 2023). "In addition, exosomal miR-429 was demonstrated to enhance the proliferation and drug resistance of ovarian cancer cells by targeting the calcium-sensing receptor (CASR)/STAT3 pathway, which indicates that miR-429 may act as a primary regulator of chemoresistance." (PMID 38002073, 2023). "In ovarian cancer cells, the presence of IL-6 induces the expression of HIF-1α through the activation of STAT3." (PMID 37501379, 2023). "Jiang and colleagues found that introducing STAT3 shRNA into A2780CP and A2780 ovarian cancer cells inhibited STAT3 gene expression." (PMID 38067351, 2023). "Doxazosin suppressed the growth of ovarian carcinoma cells and additively enhanced apoptotic cell death by IFN treatment and its effects were potentiated by reducing phosphorylation of STAT3." (PMID 37193964, 2023). "Western blot and RT-PCR analysis showed that the inhibition of STAT3 in SKOV3 and OVCAR3 ovarian cancer cells reduced the expression of CCND1, BIRC5, and VEGF." (PMID 38067351, 2023).